INS (insulin)
Diseases named in the same sentence as INS in open-access papers (continued):
Sharing a sentence is not in itself a finding about the gene and the disease.
metabolic syndrome (continued). "Prior evidence suggests that higher histidine concentrations mitigate metabolic dysregulation; for example, dietary supplementation with histidine was found to improve insulin sensitivity, possibly via the suppression of pro-inflammatory cytokine expression, in women with metabolic syndrome." (PMID 36855092, 2023). "IR might promote incidence and AAA progression by systemic factors (dyslipidemia, hyperglycemia, inflammation) as well as by the disruption of insulin signaling in endothelial cells, VSMCs and/or macrophages." (PMID 37034348, 2023). "Impaired pancreatic insulin secretion, dyslipidemia, and defects in the insulin signaling pathway in the skeletal muscle and adipose tissue that relate to the altered glucose–insulin handling and a higher prevalence of increased fetal adiposity and fetal macrosomia were observed in women with GDM." (PMID 38202146, 2023). "Interestingly, in DIO mice, apart from increasing insulin sensitivity and improving dyslipidemia, CX08005 treatment reduced leukocyte recruitment and increased blood flow in the hepatic microcirculation." (PMID 36678603, 2023). "Furthermore, due to dyslipidemia, there is an increase in triglycerides, free fatty acids, inflammatory cytokines, insulin resistance, and C-reactive protein (CRP), which increase the risk of severe COVID-19 cases and mortality." (PMID 37888519, 2023). "Additionally, a large body of evidence indicates that dietary fiber contributes in improving metabolic health status components such as hypertension, dyslipidemia, insulin sensitivity, and inflammatory biomarkers levels." (PMID 37777675, 2023). "Sex differences in renal responses to insulin may be an important determinant of how the kidney adjusts to states of hyperinsulinemia, e.g., during metabolic syndrome (MetS)." (PMID 37175762, 2023). "By mitigating oxidative stress, melatonin may reduce metabolic complications, such as hyperinsulinemia (elevated insulin levels), obesity, and dyslipidemia." (PMID 38106751, 2023). "Moreover, a study found that after the infusion of microbes from lean donors, the insulin sensitivity of recipients increased, demonstrating the favorable effect of reconstituted GM on metabolic syndrome." (PMID 36654766, 2023). "Consequently, interventions aimed at reversing the insulin resistance status of endothelial cells present promising avenues for addressing metabolic syndrome and CVD therapeutically, offering novel insights into potential treatment strategies." (PMID 38107110, 2023). "Another study investigating the association between AMH and metabolic syndrome in women with PCOS concluded that AMH was positively correlated with HDL cholesterol and SHBG and negatively correlated with glucose, insulin, blood glucose, BMI, and blood pressure." (PMID 37242163, 2023). "It is worth noting one previous study on prepubertal obese children with metabolic syndrome, which reported that cardiometabolic risk was associated with increased postprandial, but not with fasting, insulin resistance." (PMID 36674606, 2023). "An improvement in insulin sensitivity following the administration of gut microbiota from lean donors to men with metabolic syndrome has been reported, accompanied by an increase in the concentration of butyrate-producing intestinal bacteria (Roseburia intestinalis, Eubacterium hallii)." (PMID 36837875, 2023). "Further investigations are needed on the effects of artificial sweeteners on the gut microbiota, antibiotic resistance, insulin and glucose metabolism, innate immunity, and the development of some diseases, e.g., cancer, metabolic syndrome, irritable bowel syndrome, and inflammatory bowel diseases." (PMID 38276259, 2023). "In line with this, the authors of the study identified a significant association between sphingosine-1-phosphate and features of metabolic syndrome, including body fat percentage, waist circumference, total, and LDL cholesterol levels, and fasting plasma insulin." (PMID 37511095, 2023).
metabolic syndrome (continued). "Furthermore, NMR metabolomics has been used to determine metabotypes that responded to vitamin D supplementation by improving metabolic syndrome-related risk markers including CRP, insulin, and HOMA scores." (PMID 36899329, 2023). "The glucagon to insulin ratio was identified as a significant predictor of metabolic syndrome." (PMID 37762748, 2023). "In addition to glucose metabolism, a relationship between sarcopenia and metabolic syndrome has been reported, possibly because skeletal muscles secrete myokines, which increase insulin sensitivity, affect muscle physiology, and regulate the metabolism." (PMID 36545275, 2023). "Moreover, several studies documented a strong correlation between RBP4 and both IR and dyslipidemia; as it impairs glucose tolerance and insulin sensitivity and enhances the production of the gluconeogenic enzyme, phosphoenolpyruvate carboxykinase." (PMID 37180899, 2023). "Furthermore, MICT was more effective than HIIT in increasing lean body mass, improving glucose intolerance and insulin sensitivity, as well as ameliorating dyslipidemia in HFD mice." (PMID 37762143, 2023). "Individuals with high METv tended to be older and female, have lower income, a higher prevalence of hypertension, dyslipidemia, chronic kidney disease, and more advanced DM with higher fasting glucose levels and an increased number of antidiabetic medications or insulin use." (PMID 37555004, 2023). "Individuals with an unbalanced gut microbiota composition may exhibit a plethora of detrimental health outcomes: higher BMI, increased fat mass, reduced insulin sensitivity, dyslipidemia, and an increased inflammatory state." (PMID 37605183, 2023). "Similarly, in an acute trial conducted on individuals with metabolic syndrome (n = 20), the consumption of pistachios with white bread significantly lowered the glycemic response and increased insulin secretagogue levels when compared to white bread alone." (PMID 36839236, 2023). "Although there is an evident bidirectional link between NAFLD and metabolic syndrome (MS), disconnections between liver fat and insulin control have been reported specifically in PNPLA3 gene variants, which are characteristic of the Hispanic population here studied, with susceptibility to NAFLD." (PMID 36769628, 2023). "It is known that resistance activities such as push-ups or squats have effects on metabolic syndrome and lead to insulin sensitivity improvement and ALT reduction, and decreases in the cytokeratin 18 (CK18) and FGF21 levels were observed after applying this type of PA." (PMID 36902639, 2023). "Moreover, the PI3K/AKT/GSK-3ß signaling pathway activation not only improves insulin sensitivity and glucose metabolism, but also exerts a beneficial influence on dyslipidemia." (PMID 38248832, 2023). "In addition, reduced glucose plasma levels were also observed in hydroxytyrosol-treated rats, showing an improvement in insulin sensitivity and, therefore, in the metabolic syndrome evolution." (PMID 37110130, 2023). "Further, new treatments such as insulin sensitizers that affect mitochondrial pathways could disrupt progression to metabolic syndrome, inflammation, oxidative stress and depression, given shared pathways." (PMID 37841401, 2023). "It has been previously found that GH replacement therapy had favorable effects on separate components of the metabolic syndrome, apart from a possible deterioration of insulin sensitivity and glycemic control, particularly in patients with elevated body mass index." (PMID 36901984, 2023). "Together with obesity horses affected by EMS are characterized by abnormal insulin response to oral glucose (often hyperinsulinemia), hyperleptinemia, local and systemic inflammation, hypertriglyceridemia, or mild triglyceridemia and dyslipidemia." (PMID 37697311, 2023).
metabolic syndrome (continued). "A randomised switch study from TDF/FTC/NNRTI to ABC/3TC/DTG saw significant weight gain in the DTG arm, but no associated reduced insulin sensitivity or treatment-emergent metabolic syndrome." (PMID 37791109, 2023). "Some features of IR and HI such as increased hepatic glucose production are likely a consequence of reduced insulin action, while others such as hepatic steatosis and dyslipidemia are likely due to increased insulin action via signaling pathways that are not perturbed in IR." (PMID 37008938, 2023). "In conclusion, FMT does not produce any serious adverse effects and may be beneficial as an adjunctive therapy in the treatment of metabolic syndrome, especially in improving blood glucose, increasing insulin sensitivity, and HDL cholesterol." (PMID 37471410, 2023). "The SABPA cohort study found that NC was associated with blood pressure, blood glucose, lipids, and insulin levels compared to WC, and was a stronger predictor of metabolic syndrome (Mets) (independent of menopausal status) in Saharan Caucasians." (PMID 37064684, 2023). "Although different in biochemical and molecular characteristics, dysregulation of both SAT and VAT contribute to the metabolic syndrome, correlating with disruption of free fatty acid metabolism, ectopic fat deposition in organs and skeletal muscle, increased inflammation, and insulin resistance." (PMID 38140310, 2023). "In patients with dyslipidemia, the measured insulin level may be 15% higher than the actual concentration." (PMID 37241071, 2023). "The resistance to the antilipolytic effect of insulin over the number of triglycerides in excess, together with the de novo synthesis of free fatty acids in the liver, results in a progressive increase in free fatty acids and subsequent dyslipidemia." (PMID 36670674, 2023). "Also, Glucagon-like peptide-1 (GLP-1), a gut released hormone, which can protect pancreatic β-cells from apoptosis and induce insulin secretion, is attracting attention as a possible link between metabolic syndrome and brain impairment." (PMID 37457589, 2023). "A previous study found increased body weight, increased plasma insulin and leptin levels and decreased insulin sensitivity after four-week corticosterone administration via drinking water, proposing a potential animal model of the metabolic syndrome." (PMID 36756053, 2023). "Notably, insulin and adiponectin concentrations in women with T2D and dyslipidemia were improved by combined training and receiving the propolis supplement (EXR + SUPP group)." (PMID 37542207, 2023). "The ability of EVOO to decrease the risk of the metabolic syndrome and type 2 DM is related to its effects on FBG, insulin, and HOMA-IR, which can all be improved by EVOO compared with either a diet that includes an oil rich in polyunsaturated fat (sunflower oil) or a low- fat diet." (PMID 37447242, 2023). "Among the medications used after surgery were antihypertensive drugs, proton pump inhibitors (PPIs), insulin/weight-reduction injections, diet control alone, oral agents for type 2 diabetes (T2D), statins for dyslipidemia, and continuous positive airway pressure (CPAP) for OSAS." (PMID 37593300, 2023). "DCA is a bile acid derived from cholic acid by microbiota transformation and studies suggest that it is associated with numerous detrimental effects, such as inflammation, immune dysregulation, dyslipidemia, decreased insulin sensitivity and vascular calcification." (PMID 37242181, 2023). "Being underweight was associated with significantly increased risk of SCD regardless of age, sex, income level, smoking history, alcohol consumption, regular physical activity, hypertension, dyslipidemia, fasting glucose, duration of DM, use of insulin, and number of oral antidiabetic medications." (PMID 36769693, 2023).
metabolic syndrome (continued). "Insulin and insulin-like growth factors are crucial to the peripheral and central metabolism, as shown by the cellular abnormalities induced by the metabolic stress present in both T2D and metabolic syndrome." (PMID 37176104, 2023). "In addition to increasing available energy, adipose tissue can play a role in critical illness by improving insulin sensitivity, reducing dyslipidemia, and enhancing thermoregulation." (PMID 36959537, 2023). "However, significant interactions were observed with age, alcohol consumption, presence of dyslipidemia, and insulin use." (PMID 36769693, 2023). "Notably, L-carnitine has also been shown to have anti-inflammatory and antioxidant characteristics, as well as the capability to improve insulin sensitivity, support protein metabolism, maintain membrane integrity, and address dyslipidemia." (PMID 38082229, 2023). "Chlorogenic acid inhibited hepatic glucose-6-phosphatase expression and activity, decreased hepatic steatosis, and improved lipid profiles and skeletal muscle glucose uptake, which improved fasting glucose levels, glucose tolerance, insulin sensitivity, and dyslipidemia in the Leprdb/db mice." (PMID 36771347, 2023). "Several hypotheses have been proposed, such as altered insulin signaling, impaired glucose and lipid metabolism (metabolic syndrome), and reduced Aβ clearance capacity." (PMID 37762425, 2023). "In addition, it was shown that the transfer of stools from lean donor recipients into metabolic syndrome patients increased insulin sensitivity of the latter and the abundance of 16 different taxa, including Oxalobacter formigenes." (PMID 37438382, 2023). "This dysregulation of insulin signaling pathways disrupts the delicate balance of lipid metabolism, contributing to abnormalities in lipid profiles and consequently leading to the dyslipidemia observed in IR individuals." (PMID 38125279, 2023). "Dysregulation of insulin signaling at the level of the enterocyte may contribute to postprandial dyslipidemia." (PMID 38303975, 2023). "Our findings suggest that an impairment of the A/L ratio (as seen in metabolic syndrome) in the first trimester is characteristic of PE, while aberrant fetal growth in PE is not dependent on insulin sensitivity, but rather on leptin-associated pathways." (PMID 36676079, 2023). "Improved insulin sensitivity is pivotal, as it not only aids in glucose regulation but also addresses the metabolic complications often associated with PCOS, such as hyperinsulinemia and dyslipidemia." (PMID 38106751, 2023). "We hypothesized that control of increased insulin uptake by overcoming resistance may lead to improved control of metabolic syndrome in PC patients through metrics such as weight, waist circumference and serum insulin levels." (PMID 37335291, 2023). "Short-chain fatty acids, primarily acetate, propionate and butyrate are known to lower intestinal pH, which in turn can inhibit the growth of pathogenic bacteria and promote favourable metabolic effects leading to a reduction in the incidence of metabolic syndrome and improved insulin sensitivity." (PMID 36647175, 2023). "In addition, allogenic FMT using feces from metabolic syndrome donors decreased insulin sensitivity in metabolic syndrome recipients compared with using post-Roux-en-Y gastric bypass donors." (PMID 36777348, 2023). "In subjects with metabolic syndrome, most of the clinical and hormonal parameters (waist circumference, waist-height ratio, fasting blood sugar, fasting insulin, triglycerides, T3, and TSH) were significantly higher (p<0.001) as compared to those without metabolic syndrome." (PMID 37809190, 2023). "Furthermore, the glucagon to insulin ratio dropped considerably with the rise in the number of metabolic syndrome elements." (PMID 37762748, 2023).
metabolic syndrome (continued). "Consuming high phosphate-containing foods in excess may cause various noncommunicable diseases, principally abdominal or central obesity, chronically raised blood pressure, dyslipidemia, IR/impaired insulin glucose metabolism, and steatohepatitis." (PMID 36105908, 2022). "These correlations with other diseases could be attributed to significant abnormalities in blood pressure, glucose–insulin homeostasis, impaired renal and kidney function, and dyslipidemia, as shown in our study." (PMID 36355156, 2022). "The complex interplay of OSA with obesity, hypertension, dyslipidemia, and insulin resistance can contribute to metabolic syndrome and can result in elevated levels of serum insulin, increasedblood pressure, triglycerides, and lower levels of high-density lipoproteins levels." (PMID 35204981, 2022). "Hepatocyte-specific transgenic activation of arginine catabolism, or systemic administration of an anti-tumor pharmacotherapy, pegylated arginine deiminase, each promote energy expenditure and insulin sensitivity, and reduce dyslipidemia and hepatic steatosis in obese mice." (PMID 37457375, 2022). "As an inhibitor of leptin and insulin signaling, increased muscular SOCS3 expression has been suggested as a major contributor to mitochondrial dysfunction, impaired fatty acid oxidation, as associated with aging, metabolic syndrome, and inflammation." (PMID 35151349, 2022). "In addition, in Wistar rats, integration of B. adolescentis enhances visceral fat accumulation and insulin sensitivity in an experimental pattern of metabolic syndrome." (PMID 35837275, 2022). "Univariate correlations showed that myocardial glucose metabolism was positively correlated with insulin-stimulated glucose disposal (r = 0.488, P = 0.003), and negatively correlated with the presence of metabolic syndrome (r = −0.743, P < 0.0001) and with its individual components." (PMID 35845046, 2022). "A prospective study showed that FMT could increase insulin sensitivity in patients with metabolic syndrome." (PMID 35050187, 2022). "Male recipients with metabolic syndrome showed improvement in peripheral insulin sensitivity six weeks after receiving allogenic intestinal microbiota from lean donors, attributed to an increase in gut microbial diversity, including those related to butyrate-production." (PMID 35409202, 2022). "Although such approaches have yet to be implemented in humans with respect to CAD, fecal transplantation studies have shown that transfer of gut microbes from lean donors through a duodenal infusion into patients with metabolic syndrome can improve insulin sensitivity." (PMID 35870705, 2022). "In a study utilizing vasopressin receptor knockout mice being fed high fructose diets, V1b receptor null mice were found to have suppressed markers of the metabolic syndrome phenotype, including fat mass, hepatic steatosis, serum triglycerides, transaminases, insulin, and leptin." (PMID 35656391, 2022). "Notably, this finding is in agreement with another study which suggested that lower levels of this species at baseline were predictive of improvement in insulin sensitivity after fecal microbiota transplantation (FMT) in patients with metabolic syndrome." (PMID 35135549, 2022). "However, the combination of J-12 and insulin significantly reduced FBG levels in late pregnancy, and the intake of J-12 alone improved dyslipidemia, insulin, and leptin resistance (1.00 mIU/L, 9.16 ng/mL) and activated adiponectin (14.97 mg/L) in rats." (PMID 36615827, 2022). "Copeptin, the c-terminal portion of arginine vasopressin, which may be related to metabolic syndrome through altering insulin and glucagon secretion, was determined in this study." (PMID 36320894, 2022). "However, in a cross-sectional study of individuals with metabolic syndrome, plasma SAM levels were reported to be associated with increased fasting insulin levels, IR, and tumor necrosis factor-α." (PMID 36299884, 2022).